RNU6-1149P (RNA, U6 small nuclear 1149, pseudogene)
Gene: Small nuclear RNA gene on chromosome 21 (42,417,497 to 42,417,593, reverse strand). Ensembl gene ENSG00000252619.
Homologues: Orthologues: chimpanzee U6 (100% identical), macaque U6 (82% identical), rabbit U6 (78% identical), guinea pig U6 (69% identical), dog U6 (68% identical), rabbit U6 (61% identical), rabbit U6 (59% identical), rabbit U6 (58% identical), rabbit U6 (57% identical). Paralogues in human: RNU6-537P (80% identical), RNU6-1260P (79% identical), RNU6-1219P (78% identical), RNU6-1289P (78% identical), RNU6-196P (78% identical), RNU6-211P (78% identical), RNU6-310P (78% identical), RNU6-340P (78% identical), RNU6-429P (78% identical), RNU6-684P (78% identical), RNU6-1152P (77% identical), RNU6-1209P (77% identical), and 1286 more.